RNU6-854P (RNA, U6 small nuclear 854, pseudogene)
Gene: Small nuclear RNA gene on chromosome X (77,837,289 to 77,837,395, forward strand). Ensembl gene ENSG00000200906.
Homologues: Orthologues: chimpanzee U6 (99% identical), macaque U6 (93% identical). Paralogues in human: RNU6-29P (93% identical), RNU6-536P (93% identical), RNU6-73P (93% identical), RNU6-1124P (92% identical), RNU6-1152P (92% identical), RNU6-19P (92% identical), RNU6-35P (92% identical), RNU6-434P (92% identical), RNU6-656P (92% identical), RNU6-12P (91% identical), RNU6-13P (91% identical), RNU6-140P (91% identical), and 1289 more.